PPARG (peroxisome proliferator activated receptor gamma)
Diseases named in the same sentence as PPARG in open-access papers (continued):
Sharing a sentence is not in itself a finding about the gene and the disease.
neurodegenerative disease (continued). "The suppression of neuroinflammation in Cdk5 cKO mice ameliorates gliosis and neuronal loss, thus suggesting the potential beneficial effects of the PPARγ agonist pioglitazone for the treatment for neurodegenerative diseases." (PMID 24495352, 2014). "Evidence obtained from pharmacological activation of PPARγ by TZDs drugs suggests a possible therapeutic use against neurodegenerative diseases." (PMID 25246934, 2014). "Agonists of PPARγ have been used to reduce neurodegenerative changes in mice models that mimic several neurodegenerative diseases." (PMID 25246934, 2014). "Together, our results support Smurf2 as a regulator of EZH2 turnover to facilitate PPARγ expression, which is specifically required for neuron differentiation, providing a molecular mechanism for clinical applications in the neurodegenerative diseases." (PMID 23526793, 2013). "PPARγ agonists have been shown to be neuroprotective in a number of neurodegenerative diseases including PD." (PMID 22417924, 2012). "Inflammation is an important feature in the pathogenesis of a whole spectrum of neurodegenerative diseases, consequentially PPARγ agonists have the potential to provide neuroprotective effects." (PMID 22417924, 2012). "First, Douglas Feinstein (Chicago, USA) reported on the potential use of PPARγ-sparing thiazolidinediones for the treatment of neurodegenerative diseases." (PMID 22883324, 2012). "Consequently, PPARγ is viewed as an interesting target for therapeutic intervention in patients with brain injuries and neurodegenerative diseases." (PMID 36834611, 2023). "The function of PPARγ agonists in inhibiting ferroptosis may become a new therapeutic target in the treatment of neurodegenerative diseases and tumors." (PMID 35517804, 2022). "Lots of evidence showed that PPARγ could blunt microglial activation, thus controlling the inflammatory milieu in several models of neurodegenerative diseases." (PMID 35553009, 2022). "PPARγ is expected to provide a new therapeutic approach for the treatment of atherosclerotic and ischemic cerebrovascular diseases, and it is essential for the prevention of neurodegenerative diseases, including AD." (PMID 35684047, 2022). "As outlined in our study, it can be concluded that PPARγ could be exploited to prevent and/or treat inflammatory and apoptotic conditions in neurodegenerative diseases including HD." (PMID 35553009, 2022). "Indeed, it has been reported that PPARγ activation can treat and prevent neurodegenerative diseases, and that PPARγ agonists prevent LPS-induced neuronal death." (PMID 34361731, 2021). "Studies have revealed that agonist activity at peroxisome proliferator-activated receptor-gamma (PPAR-γ) has beneficial effect in neurodegenerative diseases through upregulating PGC-1α expression and attenuating inflammation, oxidative stress, and mitochondrial dysfunction." (PMID 33100954, 2020). "HSYA's protection against SIN-1-induced negative regulation of PPARγ activity may help in potentiating the control of nitrosative stress and offer new therapeutic opportunities for treating neurodegenerative diseases." (PMID 30410641, 2018). "Our present data and others have shown that PPARγ is crucial to the defensive mechanism of neurons against nitrosative stress and oxidative stress, both of which playing a role in the pathogenesis of many neurodegenerative diseases." (PMID 30410641, 2018). "NPD1 interacting with the PPARγ is hypothesized to be play a significant role in suppressing neuroinflammation and thus, is considered to be of benefit in some neurodegenerative diseases." (PMID 28109294, 2017). "Finally, secondary effects of PPARγ activators have been reported in several neurodegenerative diseases." (PMID 25246934, 2014). "These novel findings may contribute to the understanding of the effects of PPARγ on neuronal differentiation and validate the use of PPARγ activators as therapeutic agents in neurodegenerative diseases." (PMID 23741474, 2013).
neurodegenerative disease (continued). "Our findings suggest that PPARγ agonists could prove beneficial in the treatment of neurodegenerative diseases." (PMID 23185633, 2012). "Thus further studies on the regulation of NSCs by PPARγ agonists would help to determine their use in the treatment of neurodegenerative diseases." (PMID 23185633, 2012). "The activation of PPARγ in the brain may also result in metabolic side effects, such as weight gain and fluid retention, which can be problematic in the long-term treatment of neurodegenerative diseases." (PMID 40926269, 2025). "Although the cluster containing Ahnak and Plp1 was not as strongly upregulated by PPARγ ligands as by the Ser273Ala mutant, these findings suggested that inhibitors of PPARγ Ser273 phosphorylation may also be useful in the treatment of inflammation-related neurodegenerative diseases." (PMID 32695150, 2020). "Thus, keeping PPARγ function active could become particularly important for the neurons in degenerative diseases." (PMID 30410641, 2018). "Therefore, the beneficial effects of PPARγ agonist treatment in neurodegenerative diseases could be due to inhibition of Cdk5 kinase activity and a subsequent reduction in tau phosphorylation." (PMID 24495352, 2014). "As a PPARγ agonist and an insulin sensitizer, pioglitazone is widely used for the treatment of T2DM, and has also been reported to be effective in a number of neurodegenerative disease models." (PMID 23527159, 2013). "Given the complexity of the interactions between PPARγ, SIRT1, and AMPK, further investigations are necessary to elucidate the precise pathways through which QUR activates PPARγ and to determine its potential therapeutic applications in neurodegenerative diseases." (PMID 40430476, 2025). "The exact mechanism through which pioglitazone affords protection in neurodegenerative diseases has not been conclusively determined, but it is well known that this drug acts as an agonist for peroxisome proliferator-activated receptor gamma (PPARγ), a member of the nuclear hormone receptor family." (PMID 35204782, 2022). "Thus, PPARγ agonists and PGC-1α could be valuable potential therapeutic targets for neurodegenerative diseases." (PMID 25007880, 2015). "We have demonstrated earlier that PPARγ agonists ameliorate experimental allergic encephalomyelitis (EAE) model of MS by blocking inflammatory signaling networks, suggesting a physiological role for the PPARγ in the regulation of inflammation and CNS repair in neurodegenerative diseases." (PMID 23185633, 2012). "The evidence presented here supports the role of anti-oxidant mechanisms in the protective effects of PPARγ agonists in neurodegenerative diseases, but indicates that these effects may be independent of PPARγ activation." (PMID 22417924, 2012).
kidney diseases (38 papers, 2008 to 2025). "Accumulating evidence established that all PPAR members (PPARα, PPARβ/δ, and PPARγ) are implicated in the pathogenesis of kidney diseases." (PMID 40432888, 2025). "In recent years, peroxisome proliferator-activated receptor γ (PPARγ) has been found to be closely associated with hypoxia renal disease." (PMID 36420656, 2022). "The transcription levels of PPAR family proteins, PPARG upstream proteins, kidney disease-related proteins, and EMT-related TGF-Β1 protein in rat kidney tissues from each experimental group were detected by RT-qPCR." (PMID 37569334, 2023). "The results reported a protective effect of this carotenoid by down-regulating the expression of proinflammatory genes related to kidney diseases, including renin 1 and peroxisome proliferator-activated receptor gamma (PPAR-γ)." (PMID 34677429, 2021). "Other hallmarks of kidney disease are enhanced activity of Ang II, with increased AT-R1 expression and down-regulated expression of PPARγ." (PMID 20613959, 2010). "In the latest years, several articles explored theconneciton of PPARγ and the impaired function of the kidney filtration units indiabetic kidney disease." (PMID 19283081, 2008). "Therefore, there is an increasing interest in exploring natural products with PPARγ-activating potential, which can be a promising solution to developing effective and safe treatment of kidney diseases." (PMID 36339586, 2022). "In addition, PPARγ is involved in kidney disease by participating in cell proliferation, apoptosis, inflammation, oxidative stress, as well as lipid metabolism, and activation of PPARγ improves kidney injury." (PMID 36420656, 2022). "However, the role of the epigenetic modification in PPARγ function in kidney diseases still needs further exploration." (PMID 32158560, 2020). "PPARγ agonists have also been tested in humans, and seem to improve glucose tolerance and reduce the urinary albumin excretion rate, thus indirectly delaying renal disease progression." (PMID 30012954, 2018). "PPARγ belongs to a family of nuclear hormone receptors with protective role in kidney diseases." (PMID 25785827, 2015). "For example, in experiments on diabetic rats with nephropathy, treatment with PPARγ agonist reduced the occurrence of albuminuria and prevented the development of glomerulosclerosis and glomerular hypertrophy by suppressing TGF-β, VEGF, PAI-1, collagen IV, and ICAM-1." (PMID 20613990, 2010). "Besides, PPARγ can be influenced by epigenetic modification in kidney diseases." (PMID 32158560, 2020). "Finally, a better understanding of the molecular mechanisms of action of PPARγ in specific pathways together with its systemic implications may allow the development of new agonists and modulators to improve the management of kidney disease and consequently global homeostasis." (PMID 30012954, 2018). "The development of new therapies (combined or not) that exploit the beneficial effects of PPARγ activation in the treatment of renal disease are therefore warranted." (PMID 30012954, 2018). "Accumulating evidence suggested that PPARγ agonists could also provide a protection in wider spectrum of kidney diseases, such as the acute nephrotic syndrome, nondiabetic glomerulosclerosis, and the polycystic kidney." (PMID 32158560, 2020). "Additionally, the renal protective effect of PPARG agonists against nondiabetic renal disease and anticancer activities of PPARG agonist was recently reported." (PMID 25879043, 2015).
inflammation (35 papers, 2005 to 2024). Aberrant reaction of the microcirculation characterized by movement of fluid and leukocytes from the blood into extravascular tissues. "Its activation by rosiglitazone not only induces HO-1 expression but also mitigates LPS-mediated inflammatory responses, demonstrating the dual protective effects of PPARγ agonists against pulmonary inflammation." (PMID 38360670, 2024). "In this comprehensive review, we showed a complex web of signaling pathways and transcription factors that orchestrate the protective effects of PPARγ agonists against pulmonary inflammation." (PMID 38360670, 2024). "We find that during IgG-IC-induced acute lung inflammation, PPARγ expression at both RNA and protein levels is repressed, which is consistent with the results obtained from macrophages treated with IgG-IC." (PMID 33717177, 2021). "Taken together, these results demonstrate that PPARγ is a key factor that controls miR-424 and miR-503 expression in response to endothelial inflammation." (PMID 28566713, 2017). "In addition, recent studies also suggest that PPARG has a regulatory role in the control of inflammatory responses, showing the potential therapeutic applications of PPARG in inflammation-related PCa." (PMID 36795572, 2023). "Activation of PPARγ can decrease endotoxemic-induced, lipopolysaccharide-induced, and hemorrhage-induced acute pulmonary inflammation and injury through inhibition of neutrophil accumulation, ICAM-1 expression, and proinflammatory cytokine (IL-6, IL-1β) production." (PMID 27556035, 2016). "Moreover, we find that PPARγ is a novel transcriptional suppressor of Mark4 and it alleviates oxidative stress and adipose inflammation by binding to Mark4 promoter region." (PMID 26888669, 2016). "Findings from our in vitro and in vivo work revealed that PPARγ is an important pathway involved in HIV-1 brain-associated inflammation and could constitute a potential molecular target in the treatment/prevention of HIV-1 brain inflammation and HAND." (PMID 28886715, 2017). "Insummary, although the current data supports a role for PPARγ expression and activation in epithelialand immune cell types in the control of colonic inflammation, it remainsunclear whether targeting PPARγ with thiazolidinediones will be aneffective strategy for treating gut inflammation." (PMID 18615192, 2008). "The administration of natural β-carotene, in the present study, protected mice against CP-induced ALI and lung inflammation through the activation of the SIRT1 and PPARγ signaling pathway." (PMID 37018237, 2023). "Aside from cytokines and neutrophil trafficking, there are several influential signaling pathways that play a role during brain inflammation including NF-IL6, NFκB, and PPARγ." (PMID 37686333, 2023). "In another study, telmisartan was observed to attenuate brain inflammation, via M2 microglia polarization, mainly by CAMMKβ dependent AMPK activation, and partly by PPARγ activation." (PMID 30718686, 2019). "Although earlier studies showed ligand-induced activation of nuclear receptor PPARγ to promote resolution of lung inflammation, its reduced activity did not provide signs of resolution impairment in the settings investigated here." (PMID 21933390, 2011).
neurological disorders (32 papers, 2007 to 2025). "While originally characterized for its role in adipogenesis and glucose metabolism, PPARγ has been recently linked to neurological disorders such as neurodegeneration and neuro-inflammation." (PMID 32895370, 2020). "Whether targeting PPARγ alone can fully address the multifaceted mechanisms underlying neurological disorders remains to be determined." (PMID 40195204, 2025). "The ligand-dependent transcription factor PPARγ (peroxisome proliferator-activated receptor gamma) contributes to the mechanism of action of KD and has anti-inflammatory and neuroprotective effects in mammalian models of neurological disorders, including TBI." (PMID 34699541, 2021). "In mammals, the mechanism of action of KD is mediated by the transcription factor PPARγ, which has neuroprotective effects in a number of progressive neurological disorders, including TBI." (PMID 34699541, 2021). "The majority of the data available linking PPARγ with cognitive performance derives from studies on neurological diseases, where once again the role of PPARγ activation in cognition is apparent." (PMID 31614739, 2019). "Evidence suggests that targeting Peroxisome Proliferator-Activated Receptor-gamma (PPARγ) can be anti-inflammatory in neurological disorders." (PMID 31263138, 2019). "Compelling evidence suggests that PPARγ exerts anti-inflammatory properties in neurological disorders." (PMID 28886715, 2017). "PPARγ is a known regulator of mitochondrial function and energy metabolism and has been previously proposed as therapeutic target for the improvement of energy metabolism in neurological disorders." (PMID 41327250, 2025). "There is some evidence indicating that PPARγ plays a beneficial role in various neurological diseases and that its activation may represent a potential target for the treatment of numerous acute and chronic neurological diseases." (PMID 37958932, 2023). "Amongst the substantial TFs associated with the DEGs were early growth response 1 (EGR1), signal transducer and activator of transcription 3 (STAT3) and peroxisome proliferator activated receptor gamma (PPARG), which are involved in different neurological diseases." (PMID 32967368, 2020). "Some doctors and pharmacists formerly have given high doses of drugs to patients thinking the PPARγ agonists with less BBB permeability could be used to treat neurological disease as long as they increased the dose <10-fold." (PMID 32138198, 2020). "In addition, PPARγ agonists have recently been reported to lower the incidence of a number of neurological disorders." (PMID 28208577, 2017). "PPARγ agonists have also shown significant favorable effects in models of neurological diseases." (PMID 29182629, 2017). "We discuss the mechanisms underlying those beneficial effects in particular in relation to mitochondrial function, antioxidant defence, cell death and inflammation, and suggest that the PPARγ agonists show significant promise as therapeutic agents in otherwise intractable neurological disease." (PMID 27352979, 2016). "Future work will investigate the significance of the PPARγ-BDNF signaling on ameliorating behavior and synaptic plasticity in neurological diseases by inhibiting the BDNF receptor (TrkB)." (PMID 31614739, 2019). "PPARγ is a known modulator of mitochondrial function and energy homeostasis and its agonist PIO has been proposed to enhance mitochondrial biogenesis and improve energy metabolism in neurological disorders." (PMID 41327250, 2025). "In conclusion, the excellent BBB permeability of ELB00824 provides a reasonable therapeutic window for neurological diseases, while other PPARγ agonists likely do not." (PMID 32138198, 2020). "Although the reasons were generally not reported, the most logical reason is that current PPARγ drugs have limited therapeutic windows in neurological disease treatment, i.e., a range of doses at which a medication is effective without unacceptable adverse events." (PMID 32138198, 2020).
liver (23 papers, 2008 to 2025). "The PPARG gene was also linked to many of the significant related terms highlighted by the disease association analysis (gastrointestinal neoplasms, intestinal diseases, inflammation and gastrointestinal diseases)." (PMID 29703268, 2018). "Peroxisome proliferator-activated receptor γ (PPARγ), a ligand-activated nuclear transcription factor, has been implicated in colorectal carcinogenesis, although its exact role remains unclear." (PMID 30186819, 2018). "The data presented show the upregulation of inflammation marker mRNA expression in metastatic-derived colorectal tumourspheres after oxaliplatin treatment, except PPARG." (PMID 36835258, 2023). "Several studies demonstrated that PPARγ activation attenuates both alcoholic and non-alcoholic fatty liver injury." (PMID 31546643, 2019). "In this paper, we introduce the structure, organization, distribution, ligands, and function of PPARγ briefly and review the correlation between PPARγ receptor and digestive system tumor." (PMID 29483923, 2018). "In the present study, using rat middle cerebral artery occlusion model, we found that curcumin was a potent PPARγ agonist in that it upregulated PPARγ expression and PPARγ-PPRE binding activity." (PMID 23762140, 2013). "This decrease of CCL20, IL-8 and PPARG gene expression and the high proliferation status of primary colorectal tumourspheres after oxaliplatin treatment strongly correlate with a metastatic phenotype, as we observed in our TNMplot data for normal, tumorous, and metastatic tissues." (PMID 36835258, 2023). "In summary, PPARγ is closely related to digestive system tumors." (PMID 29483923, 2018). "Accordingly, the downregulation of PPARγ we first report here in human PSCs after CHG exposure may contribute to the other signals resulting in islet-specific pancreas fibrosis in diabetic patients." (PMID 26010611, 2015). "This suggests that PPARγ seemingly plays no significant role in colorectal carcinogenesis." (PMID 30186819, 2018).